PDE2A (phosphodiesterase 2A)
Diseases named in the same sentence as PDE2A in open-access papers (continued):
Sharing a sentence is not in itself a finding about the gene and the disease.
Alzheimer disease (5 papers, 2015 to 2021). A progressive, neurodegenerative disease characterized by loss of function and death of nerve cells in several areas of the brain leading to loss of cognitive function such as memory and language. "Consistent with this view, small molecule inhibitors of PDE2A showed efficacy in models of Alzheimer’s disease." (PMID 34412701, 2021). "Hence, PDE2A inhibitors might be promising compounds regarding drug development for treatment of neurodegenerative disorders such as Alzheimer’s disease (AD)." (PMID 26016549, 2015).
epilepsy (5 papers, 2021 to 2025). A brain disorder characterized by episodes of abnormally increased neuronal discharge resulting in transient episodes of sensory or motor neurological dysfunction, or psychic dysfunction. "Dominant mutations in GNAO1, GNB1, and PDE2A have been associated to a complex early-onset neurological disorder characterized by a variable association of hyperkinetic MD, epilepsy, and developmental delay generally evolving into intellectual disability." (PMID 36003298, 2022). "PDE2A homozygous variants have been confirmed to cause a complex infantile syndrome consisting of childhood‐onset chorea, paroxysmal dyskinesia with cognitive disability, and electroencephalographic abnormalities or overt epilepsy." (PMID 40492975, 2025). "Recently, PDE2A homozygous mutations have been confirmed to cause a complex infantile syndrome consisting of paroxysmal dyskinesia with cognitive disability and electroencephalographic abnormalities or overt epilepsy." (PMID 34155691, 2021). "Finally, Salpietro et al9 have demonstrated PDE2A homozygous mutations in a single case with childhood‐onset chorea with epilepsy and cognitive impairment." (PMID 34155691, 2021). "Epilepsy can be prominent in GNB1 and GNAO1 encephalopathy, while it is anecdotical in individuals with HPCA, PDE2A, and PDE10A pathogenic variants." (PMID 36003298, 2022). "While the clinical phenotype associated with ADCY5 and GNAL is characterized by movement disorder in the absence of epilepsy, GNAO1, GNB1, PDE2A, PDE10A, and HPCA have a broader clinical phenotype, encompassing movement disorder, epilepsy, and neurodevelopmental disorders." (PMID 36003298, 2022).
paroxysmal dyskinesia (5 papers, 2018 to 2025). Paroxysmal dyskinesia (PD) is a rare heterogenous group of movement disorders manifesting as abnormal involuntary movements that recur episodically and last only a brief time. "Biallelic PDE2A mutations cause a neurodevelopmental disorder with paroxysmal dyskinesia or seizures (MIM #619150)." (PMID 36003298, 2022).
colorectal cancer (4 papers, 2020 to 2024). A primary or metastatic malignant neoplasm that affects the colon or rectum. "Overexpression of PDE2A was associated with vascular invasion in colorectal cancer cell lines, finds overexpressed PDE2A associated with vascular invasion in colorectal cancer cell lines." (PMID 32351997, 2020). "The results of PDE2A expression in liver cancer, osteosarcoma, glioblastoma, and colorectal cancer were consistent with those reported in prior research." (PMID 39699377, 2024). "A different study of colorectal cancer presents evidence for differential transcriptional regulation of pri-miR-139 transcripts independent of PDE2A." (PMID 35269391, 2022).
dementia (4 papers, 2019 to 2022). Loss of intellectual abilities interfering with an individual's social and occupational functions. "The TBI‐associated dementia‐related increase in PDE expression is unique to PDE11A in that PDE2A, PDE5A, and PDE10A expression remained unchanged." (PMID 36073342, 2022).
Intellectual disability (4 papers, 2021 to 2023). "Homozygous mutations in PDE2A have been shown to be associated with neurodevelopmental and intellectual disability." (PMID 37605207, 2023). "Indeed, mutations of PDE2A have been found associated with intellectual disability and PDE2A seems to have a prominent role in memory disorders." (PMID 35338117, 2022). "Global developmental delay and subsequent moderate to severe intellectual disability are observed in almost all patients with GNB1, GNAO1, PDE2A, and HPCA variants." (PMID 36003298, 2022).
liver cancer (4 papers, 2020 to 2024). An epithelial or non-epithelial malignant neoplasm that arises from the liver. "There are also multiple reports found that PDE2A combined with other genes are a promising prognostic biomarker, such as for bladder cancer, metastatic colorectal cancer, and liver cancer." (PMID 36611861, 2022). "Finally, activation of the biomarker PDE2A significantly attenuated migration and epithelial–mesenchymal transition in the HepG2 liver cancer cell line." (PMID 36054420, 2022).
osteosarcoma (4 papers, 2013 to 2024). A usually aggressive malignant bone-forming mesenchymal neoplasm, predominantly affecting adolescents and young adults. "Specifically, PDE2A significantly regulates the growth and invasion of human breast cancer, malignant melanoma cells, osteosarcoma cells, and colon cancer." (PMID 36611861, 2022). "PDE2A mRNA expression was confirmed in the human brain, heart, vascular endothelial cells, and human MG-63 osteosarcoma cells, but has not been reported in malignant melanoma cells." (PMID 23381931, 2013).
autism spectrum disorder (3 papers, 2021 to 2023). A spectrum of developmental disorders that includes autism, and Asperger syndrome. "We also observed PDEs (which hydrolyzes both cAMP and cGMP) was associated with psychiatric disorders [OR of PDE1A was 1.0836 for autism spectrum disorder; OR of PDE2A was 0.8968 for Tourette syndrome (TS) and 0.9449 for SCZ; and OR of PDE3A was 0.9796 for MDD; P < 0.05]." (PMID 37605207, 2023).
cardiac hypertrophy (3 papers, 2017 to 2022). "It is interesting that upregulation of miR-341, miR-1188 and Pde2a have all been linked to cardiac hypertrophy or heart failure." (PMID 32647133, 2020). "On the other hand, PDE2A inhibition suppresses cardiac hypertrophy induced by norepinephrine in rats." (PMID 35479330, 2022). "Increased PDE2A expression was reported both in rodents and in human heart failure and PDE2A inhibition was shown to reduce cardiac hypertrophic remodelling in a mouse model of cardiac hypertrophy, indicating that PDE2A inhibition may be of therapeutic value in this context." (PMID 28463107, 2017). "Cardiac PDE2A expressions increase in rat cardiac hypertrophy and also in human ischemic or non-ischemic heart failure." (PMID 35479330, 2022).
hepatocellular carcinoma (3 papers, 2022 to 2024). A malignant tumor that arises from hepatocytes. "Specifically, PDE2A has the potential to regulate the proliferation of hepatocellular carcinoma cells by modulating mitochondrial morphology and ATP content." (PMID 39699377, 2024). "This study aimed to estimate the prognostic significance and biological effects of PDE2A on hepatocellular carcinoma (HCC)." (PMID 36611861, 2022). "We also found that PDE2A might play a role in the metastasis of hepatocellular carcinoma." (PMID 36054420, 2022). "Consistently, activation of PDE2A, one of genes in this model, reversed the expression of EMT signatures and repressed the cell invasion in hepatocellular carcinoma cells." (PMID 36054420, 2022).
malignant melanoma (3 papers, 2013 to 2022). "Moreover, PDE2A plays a key role in cancer progression, including colorectal cancer, melanoma, and so on." (PMID 36611861, 2022).
Obesity (3 papers, 2019 to 2021). Accumulation of substantial excess body fat. "The results revealed that 18 of the DMR genes were associated with addiction and obesity (ADCY3; ADCY9; ATF4; CDK5R1; CHRNB2; GABRD; GABRG3; GNB1; GNB3; GRK5; HDAC4; HDAC9; MAP2K1; PDE11A; PDE2A; PDE3A; PPP1CA; SLC6A3)." (PMID 34389046, 2021). "Our results suggest that PDE2A inhibition can promote a ‘fat-burning’ phenotype and may be an effective approach to retain thermogenic beige adipocytes to control obesity." (PMID 33087821, 2020). "Until now, the specific roles of ANO2, CAMK2D, SLC8A1, PDE2A, CALML3, GNG7, and CALML6 genes in olfactory-related dietary patterns and obesity in humans have not been apparently explored; therefore, further investigation in these research areas is warranted." (PMID 31057674, 2019).
Parkinson disease (3 papers, 2021 to 2024). A progressive degenerative disorder of the central nervous system characterized by loss of dopamine producing neurons in the substantia nigra and the presence of Lewy bodies in the substantia nigra and locus coeruleus. "In conclusion, both PDE inhibition via the PDE2A inhibitor PF05180999 and Gucy2C activation via guanylin effectively alleviate motor complications induced by dopamine deafferentation in the 6-OHDA Parkinson's disease mouse model, to a similar extent as the gold standard treatment, L-DOPA." (PMID 39456033, 2024). "Furthermore, both PDE2A inhibition and GUCY2C activation ameliorated motor impairments in a Parkinson’s disease mouse model with partial 6-OHDA lesions." (PMID 39456033, 2024).
adrenocortical tumors (2 papers, 2020 to 2025). "In hypercortisolism patients, PDE2A mRNA and PDE2A protein levels have been found to be upregulated in adrenocortical tumors harboring CTNNB1 mutations compared with wild-type adrenocortical tissues." (PMID 41511347, 2025). "In the present work, when the transcriptome analysis was accessed, a decrease of PDE2A, PDE5A, and PDE8A expression and a significant overexpression of PDE4B and PDE8B was observed in adrenocortical tumors, compared to normal adrenal tissue." (PMID 32098292, 2020).
anemia (2 papers, 2020 to 2024). A reduction in the number of red blood cells, the amount of hemoglobin, and/or the volume of packed red blood cells. "The consequent failure of erythrocytes production results in an anemia that is probably the principal cause of the death of PDE2A−/− embryos." (PMID 32326334, 2020). "Knockout mouse models for the different PDE isoforms have been generated and up to date, the Pde2A knockout mouse is the only embryonically lethal, most likely due to an extremely reduced liver size, impairment of the hepatic niche, and elevated anemia." (PMID 38395995, 2024). "Morphological examination of H89-treated Pde2A−/− E14.5 embryos showed anemia, hemorrhages, and reduced liver size like not-treated embryos." (PMID 38395995, 2024). "Both drugs were not able to prevent the gross phenotypes of Pde2A knockout embryos such as liver size, anemia, and hemorrhages." (PMID 38395995, 2024).
diabetes (2 papers, 2017 to 2023). "It is worth noting that the roles of PTPRN2, ASTN2, GRIN1, SLC6A18, and PDE2A in influencing FPG levels or diabetes had previously been suggested." (PMID 37461060, 2023). "All except phosphodiesterase 2A (PDE2A) and Ras-related associated with diabetes (RRAD) were also differently expressed in diabetic versus healthy left ventricles." (PMID 28727746, 2017).
diffuse large B-cell lymphoma (2 papers, 2022 to 2024). "Interestingly, the only two types of cancers with high PDE2A expression were Lymphoid Neoplasm Diffuse Large B-cell Lymphoma (DLBC) and Thymoma (THYM), both immune system cancers." (PMID 36611861, 2022).
glioblastoma (2 papers, 2024). The most malignant astrocytic tumor (WHO grade IV). "In human glioblastoma tissues, miR-139 expression was associated with PDE2A transcription and shared correlation of expression levels." (PMID 38355819, 2024). "However, the overexpression of miR-139 increased the mRNA levels of PDE2A and pre-miR-139 in glioblastoma cell lines." (PMID 38355819, 2024). "In addition to the dependency of expression, both miR-139 and PDE2A act synergistically in glioblastoma cells by repressing detrimental Wnt/β-catenin signaling and reducing the tumorigenesis of gliomas." (PMID 38355819, 2024).
heart failure (2 papers, 2017 to 2020). Inability of the heart to pump blood at an adequate rate to meet tissue metabolic requirements. "Although no change in miR-1188-3p was observed in the present study (data not shown; miR-341 not investigated), qPCR showed evidence of upregulation of Pde2a mRNA in the sinus node, but not ventricle, in heart failure." (PMID 32647133, 2020).
Hypertension (2 papers, 2016 to 2022). The presence of chronic increased pressure in the systemic arterial system. "When taken together, these results suggest that site-specific inhibition of PDE2A and PDE6D at the outer mitochondrial membrane may provide a therapeutic target to ameliorate cardiac sympathetic impairment during the onset of hypertension." (PMID 35506379, 2022). "Importantly, Pde2a knockout mice do not survive past 17–18 days gestation; Pde2a heterozygote mice are not known to develop ACTs or even hypertension." (PMID 27625633, 2016).
Kawasaki disease (2 papers, 2015 to 2019). A rare inflammatory disease characterized by an acute febrile, systemic, self-limiting, medium-vessel vasculitis primarily affecting children. "CYFIP2 (cytoplasmic FMR1-interacting protein 2) forms part of the VEGFA–VEGFR2 pathway and is associated in humans with susceptibility to Kawasaki disease and coronary artery lesions, interacting with PDE2A so that high-risk allele combinations account for 67% of cases in this human population." (PMID 31683933, 2019). "Likewise, the link between PDE2A (rs341058) SNP and Kawasaki disease found in this study, is to our knowledge, a novel finding." (PMID 26619243, 2015).
non-small cell lung carcinoma (2 papers, 2020 to 2025). A group of at least three distinct histological types of lung cancer, including non-small cell squamous cell carcinoma, adenocarcinoma, and large cell carcinoma. "It has been reported that miR-139 is epigenetically silenced by histone H3 lysine 27 trimethylation (H3K27me3) of its host gene PDE2A in non-small cell lung cancer, and that this process is independent of promoter DNA methylation." (PMID 31992823, 2020). "However, regarding the functional importance of PDE2A as suggested by embryonic lethality of PDE2A knockout mice, PDE2A or miR-139-5p may play functional roles in the pathogenesis of NEUROD1-positive SCLC, as reported in non-small-cell lung cancer cells." (PMID 40595415, 2025).
acute respiratory distress syndrome (1 paper, 2025). Progressive and life-threatening pulmonary distress in the absence of an underlying pulmonary condition, usually following major trauma or surgery. "PDE2A's role in developing lung injury through disrupted endothelial membrane barriers likely reflects the upregulation of this gene in COVID‐19 patients and the increased risk for pulmonary complications such as acute respiratory distress syndrome (ARDS)." (PMID 40476695, 2025).
adrenal Cushing’s syndrome (1 paper, 2020). "Genome-wide associations studies demonstrate that PDE2A, PDE8B, and PDE11A modulate steroidogenesis and are associated with adrenal Cushing’s syndrome and/or bilateral adrenal hyperplasia." (PMID 32098292, 2020).
adrenal hyperplasia (1 paper, 2026). "In primary aldosteronism, recent studies-including data from our group-suggest that germline variants in PDE2A and PDE3B may contribute to bilateral adrenal hyperplasia and autonomous aldosterone production by modulating intracellular cAMP levels." (PMID 41816209, 2026).
adrenal tumor (1 paper, 2020). "Transcriptome profiling of pediatric ACTs (n = 16) and normal adrenal cortex samples (n = 6) revealed that PDE2A, PDE6D, PDE8A, and PDE9A are highly expressed in both normal and adrenal tumor tissue, compared to other PDE family members." (PMID 32098292, 2020).
anorexia nervosa (1 paper, 2023). A disorder most often seen in adolescent females characterized by a refusal to maintain a minimally normal body weight, an intense fear of gaining weight, a disturbance in body image, and, in postmenarcheal females, the development of amenorrhea. "Furthermore, psychiatric disorders also had some causal effects on PDEs [obsessive–compulsive disorder on increased PDE6D and decreased PDE2A and PDE4D; anorexia nervosa on decreased PDE9A]." (PMID 37605207, 2023).
Arthritis (1 paper, 2013). Inflammation of a joint. "This QTL has also conservation of synteny with a human region containing genes associated with arthritis such as PRKCB1 (protein kinase C, beta 1) and PDE2A (phosphodiesterase 2A, cGMP-stimulated)." (PMID 24146764, 2013).
autoimmune disease (1 paper, 2021). A disorder resulting from loss of function or tissue destruction of an organ or multiple organs, arising from humoral or cellular immune responses of the individual to their own tissue constituents. "Interestingly, we could also confirm PDE2A upregulation in Tcon at the mRNA level in a more relevant in vivo T cell stimulation context during EAE, indicating that PDE2A might be important for T cell activation in inflammatory or autoimmune diseases." (PMID 34675812, 2021).
cervical cancer (1 paper, 2020). A primary or metastatic malignant neoplasm involving the cervix. "PDE2A also presents a high expression in HeLa cell lines, one of cervical cancer cell lines." (PMID 32351997, 2020).
congenital heart disease (1 paper, 2025). A heart disease that is present at birth. "Furthermore, the LOF variants identified in the low-LOUEF score genes FAM91A1, INTS8, and PDE2A have not been previously linked to congenital heart disease and are newly reported in this study." (PMID 40406060, 2025).
coronary atherosclerosis (1 paper, 2022). Atherosclerosis of the coronary vasculature. "Actually, due to its extensive functions, PDE2A has already become a potential target for coronary atherosclerosis, psychiatric disease, and metabolic disease." (PMID 36611861, 2022).
diabetic cardiomyopathy (1 paper, 2023). Diabetic cardiomyopathy is a disorder of the heart muscle in people with diabetes. "Early and specific upregulation of cardiac PDE2A gene expression was noted in diabetic cardiomyopathy." (PMID 37461060, 2023).
infantile spasms (1 paper, 2022). A rare epilepsy syndrome characterized by onset of epileptic spasms in infants between 2 and 12 months of age, and rarely up to 24 months. "DEE, described in the literature as Ohtahara syndrome, infantile spasms, or EIFMS can be the epileptic presentation of GNAO1, GNB1, and PDE2A." (PMID 36003298, 2022).
leukemia (1 paper, 2022). A malignant (clonal) hematologic disorder, involving hematopoietic stem cells and characterized by the presence of primitive or atypical myeloid or lymphoid cells in the bone marrow and the blood. "In addition, our data in MLL-AF9 leukemia, where Pde2a is normally expressed and spliced but miR-139 levels are strongly decreased, can only be explained by reduced pri-miR-139 stability and/or processing." (PMID 35269391, 2022).
multiple sclerosis (1 paper, 2021). A progressive autoimmune disorder affecting the central nervous system resulting in demyelination. "Indeed, in this model of multiple sclerosis we could detect a 2-fold induction of Pde2a in Tcon, suggesting that this mechanism might play a role in T cell activation after autoantigen immunization." (PMID 34675812, 2021).
nicotine addiction (1 paper, 2021). "PDE2A and PDE10A, the two proteins comprising the morphine addiction KEGG pathway that was upregulated in male VTA after chronic nicotine and withdrawal, can modulate dopaminergic signaling but have not been linked to nicotine addiction directly." (PMID 34335180, 2021).
ovarian serous cystadenocarcinoma (1 paper, 2024). A malignant serous cystic epithelial neoplasm arising from the ovary. "Additionally, PDE2A expression was closely related to the prognosis of cancers such as stomach adenocarcinoma (STAD), ovarian serous cystadenocarcinoma (OV), and liver hepatocellular carcinoma (LIHC)." (PMID 39699377, 2024).
paraganglioma (1 paper, 2024). A benign or malignant neoplasm arising from paraganglia located along the sympathetic or parasympathetic nerves. "Our findings revealed a significant increase in the methylation of PDE2A in specific tumor tissues, such as KIRP, pheochromocytoma and paraganglioma (PCPG), PRAD, TGCT, and THCA." (PMID 39699377, 2024).